CD2 (CD2 molecule)
Diseases named in the same sentence as CD2 in open-access papers (continued):
Sharing a sentence is not in itself a finding about the gene and the disease.
tumor (continued). "Our finding that TruCs and STARs can more efficiently exploit CD2 to achieve higher antigen sensitivities is consistent with the finding that a STAR outperformed an eTruC and that both outperformed CARs in an in vivo xenograft tumor model." (PMID 36598945, 2023). "Multiple costimulation modules (e.g., CD2, ICOS, and YMFM-CD28) may benefit CAR-T cell functionality and help counteract the acquired mechanism of tumor resistance and tumor-dependent CAR-T cell suppression." (PMID 35205827, 2022). "Not surprisingly, CD8+ tumor-infiltrating lymphocytes (TILs) in human cancers are characterized by a quantitatively lower expression of CD2, and CD2 mRNA levels in these cells are negatively correlated with exhaustion." (PMID 35881486, 2022). "Briefly, tumor cells in AITL/FHTCL demonstrated a very characteristic immunophenotypic signature with positive expressions of CD2, CD4, CD5, CD45, and heterogeneous CD7 but negative expressions of surface CD3, CD8, CD16, CD56, CD25, CD26, and CD30." (PMID 35299754, 2022). "Studies have shown that adequate density of mature DC in the tumor can prolong the survival of GC patients, and higher CD1/CD2 ratio and lower DC2 cell level are negatively correlated with the degree of tumor differentiation, degree of Foxp3+ Treg cells invasion and the risk of lymphatic metastasis." (PMID 35402261, 2022). "We found that, in addition to interacting with CD2, CD58 was co-expressed and physically interacted with HOXB family genes (HOXB2, HOXB3, and HOXB5), AKAP12, CLIC1, CPNE3, etc., which were reported to be involved in tumor initiation and progression." (PMID 34193136, 2021). "Genes upregulated in both tumor and TAS of BA PCa patients as compared to WA included cell cycle markers CD19, CD2, CD53 and CD80, interferon response factor 8 (IRF8), phosphoinositide 3-kinase (PIK3CA), mechanistic target of rapamycin (mTOR), and metastasis-associated protein S100A4." (PMID 34316327, 2021). "There has been one other study where MCF-10A cells transformed with Cd2+ produce tumor transplants without any evidence of squamous differentiation." (PMID 33062196, 2020). "Finally, we investigated the connection between tumor grades and hub genes, in which LCK, CD2, CD3D, IFNG, CD8A, and CCL5 showed significant correlation with different tumor grades (p < 0.05), with grade increase corresponding to increased gene expression." (PMID 32081834, 2020). "Resistance of tumor cells to cytarabine correlated with the expression of Ki-67 (r = 0.33) and T-cell markers (CD2, r = 0.22; CD3, r = 0.25; and CD5, r = 0.14), but not with immaturity markers." (PMID 31067780, 2019). "CD2 and ITGAL could mediate cell adhesion between immune cells and other types of cells and trigger cytotoxic function against tumor." (PMID 30333226, 2018). "Tumor cells were commonly positive for TDT (21/26, 80.8%), CD3 (29/31, 93.5%), and CD7 (25/27, 92.6%), and they were variably positive for CD5 (16/24, 66.7%), CD99 (14/19, 73.7%), CD2 (12/18, 66.7%), and CD1a (13/21, 61.9%)." (PMID 28566711, 2017). "TFF2 upregulated ApoE but ApoE−/−/CD2–Tff2 mice did not develop significantly more tumours than CD2–Tff2 mice, suggesting some functional redundancy within this system." (PMID 26841680, 2016). "Global transcriptome studies on the spleen with and without the impact of the tumor surprisingly revealed up-regulated immune related functions in old hosts with CD2, CD3ε, CCL5, and CCL19 being key T-cell related factors." (PMID 26497558, 2015). "In most cases this cut-off correlated well with previous direct analyses for gene rearrangement, although rearrangements of Myc detected by Southern blot in two of the CD2-Runx2 tumours analysed here failed to register in the splinkerette/454 analysis." (PMID 24586197, 2014).
tumor (continued). "Following tumor cell disassociation, tumor cell samples were incubated with anti-CD44, anti-CD24, and anti-lineage mixture antibodies (PE-conjugated anti-CD2, CD3, CD10, CD16, CD18, CD31, and CD 140b), and then labeled by Aldefluor assay, and analyzed using MoFlo Astrios flow cytometry." (PMID 26932376, 2014). "MAPKs are also likely to be involved in molecular mechanisms for the action of Cd2+, as it was reported that the activation of ERK1/2, JNK, and p38 MAPK occurs in renal cells (mesangial or glomerular), macrophages, and tumor cell lineages." (PMID 18629305, 2008). "In HCC, sinusoidal-type vessels were positive for vitronectin and αvβ3 was detected on tumour vessels but not on CD2+ lymphocytes." (PMID 17088900, 2006). "As CD59 can interact with CD2 on T cells, there may even be a selective pressure against CD59 expression on tumour cells to avoid interaction with T cells." (PMID 15655555, 2005). "Tumor immunophenotype was characterized by a strong expression of conventional myeloid antigens (CD13, CD33, CD15, MPO), although no monocytic (CD14, CD64, CD11c, CD11b, lysozyme), megakaryoblastic (CD61, CD41) and lymphoid (CD7, CD19, iCD79a, CD56, CD2) markers were found." (PMID 36980947, 2023). "Corroborating this assumption, our data show that whole platelets, as well as tumour cell-induced releasates, evoked Treg differentiation from CD3/CD28/CD2 stimulated CD4+ T cells, although further cell types than regulatory T cells might contribute to IL-10 release from PBMCs." (PMID 35285006, 2022). "However, the expression of the tumour‐sensing NK cell‐activating receptors NKp30, NKG2D and DNAX accessory molecule‐1 (DNAM‐1) and the surface molecules tetherin/CD317 and CD2 were all significantly reduced on the GBM tumour‐derived NK cells compared to those from matched peripheral blood." (PMID 31784984, 2020). "The Actin>CD2>Gal4 “flip-out” chromosome was used in combination with a UAS-GFP transgene and a transgene carrying a dominant-negative form of dome that lacks the C-terminal tail (UAS-domeΔCYT) to produce GFP-positive/domeΔCYT-expressing clones in the background of an ept tumor." (PMID 19787055, 2009). "CD2 expression was significantly positively correlated with TMB (p < 0.001, ρSpearman= 0.14), Regarding the analysis of clinicopathological characteristics, CD2 expression was associated with tumor size to some extent, but not with overall TNM stage, lymph node status, or distant metastasis." (PMID 33968066, 2021). "However, the anti-CD2 tracer resulted in systemic T cell depletion and lack of anti-tumor activity, even without an intact Fc region, highlighting the impact antibodies and their fragments may have on cell surface receptors." (PMID 32582173, 2020). "This could explain why the decrease in CD3 (T-cells) and CD2 (T-cells, B-cells, NK cells) was more pronounced than that of CD8α (cytotoxic T-cells, NK cells, subset of DC), CD68 (macrophages, neutrophils, DC, myeloid progenitors), and CD163 (pro-tumor macrophages, M2)." (PMID 26374556, 2015). "In addition, NKTCL and ANKCL tumor cellsnearly always express CD2 and less often CD7 and CD8, but not CD4 and CD5.From the markers usually used to identify NK-cells, CD56 is the mostfrequently positive, whereas CD16 expression is variable, and CD57 is almostnever found." (PMID 23816348, 2013). "While overexpression of CD2 enhances the affinity between CAR-T cells and tumor cells, ensuring that this enhancement does not lead to excessive on-target, off-tumor toxicity, potentially harming healthy tissues expressing the target antigen, is vital." (PMID 40615696, 2025). "Low CD2 and CD8 expression on nonlytic TILs abrogates conjugation and subsequent IS formation with cognate target tumor cells." (PMID 39349829, 2024). "Tumor cells in NKCL were consistently negative for CD3, CD4, and CD5 and showed moderate CD2, CD38, CD56, and CD94 and heterogeneous expressions of CD7, CD8, CD16, and CD26." (PMID 35299754, 2022).
tumor (continued). "Then, the qRT-PCR and western blotting were applied to detect the expression differences of CD2, CD3D, and CD3E in tumor tissues from recurrence and no recurrence patients." (PMID 36146529, 2022). "We quantified the basal migration of CAR T cells in the absence of tumor cells by TIMING and then quantified a posteriori the cell surface abundance of CD2 and CD244 by fluorescent immunostaining and microscopy." (PMID 35881486, 2022). "Immunohistochemically, the tumor cells of EATL are positive with antibodies directed against CD3, CD2, CD5, and CD8, but negative with CD56." (PMID 33546043, 2021). "Compared with normal control tissues, the expression level of CD3D and CD2 in tumor tissues were not significantly different, while the expression levels of CD3E, CD3G, CCL5, CXCR6 and LCK in tumor tissues were lower than those in normal tissues (P < 0.05)." (PMID 34218795, 2021). "The assessment of the new immune gene signature (CD2, CD3D, CD3E, and CXCRC6) in the CSCC cohort per tumor stage was not possible because sample size was too low for a meaningful analysis when we filtered data by stage." (PMID 34692491, 2021). "Immunohistochemically, tumor cells are characterized by CD30, ALK, CD5, TIA-1, Granzyme B, EMA positive staining, and CD2, CD3, CD7, CD4, CD8, CD20, CD79a negative staining." (PMID 27612448, 2016). "Immunohistochemically, the tumor cells tend to express CD56, cytoplasmic CD3ε, CD2, cytotoxic granule proteins, granzyme B, and TIA-1 but not surface CD3." (PMID 23958352, 2013). "While tumor growth was not effectively controlled in all treatment groups, possibly due to an overwhelming initial tumor burden, the group treated with CD19-BBζ + CD2 CAR-T cells presented the lowest tumor burden and a trend toward prolonged survival." (PMID 40615696, 2025).
cancer (42 papers, 2012 to 2025). A tumor composed of atypical neoplastic, often pleomorphic cells that invade other tissues. "Among the validated substrate candidates are the cancer-related ERBB2 as well as the immune system-related CD2, CD68, and CD86." (PMID 40593564, 2025). "Efforts to exploit the costimulatory activity of CD2 in cancer immunotherapy were initiated with the concept of a bispecific antibody (BsAb) that targets both CD2 and the tumor antigen epidermal growth factor receptor (EGFR)." (PMID 39349829, 2024). "To test the efficacy of UCART2 against cancer cells from patients, we established a CD2+ primary T-ALL xenograft model." (PMID 37798328, 2023). "In contrast, CD2 is expressed on >99% of T-cells and downregulates at a lower frequency than other pan-T cell markers in cancer cells, providing an attractive therapeutic target." (PMID 37798328, 2023). "T cells undergoing beta-selection differentiate via sequential expression of co-receptors CD28, CD5, and CD2, exposing new signalling controls that are disrupted by a cancer therapeutic." (PMID 36283704, 2023). "Although the positive significance of CD2 is highlighted from pan-cancer studies, it was inferred to merely reflect the presence of infiltrating lymphocytes." (PMID 35881486, 2022). "The broad expression of CD58, CD112 and CD155 on cancer cells provided a rationale to assess CD2::CD28 and CD226::CD28 chimeras." (PMID 29707134, 2018). "Our cancer model also revealed increased expression of 2B4, a CD2 Ig superfamily member, following infection." (PMID 24796533, 2014). "When comparing the antigen recognition ability of the TCR and CAR using the C9V variant (9 V) of the cancer testis peptide antigen recognized by the 1 G4 TCR and D52N scFv, TCRs utilizing adhesion molecules, such as CD2 or LFA-1, demonstrated greater antigen recognition." (PMID 39349829, 2024). "Moreover, Rad51 inhibition can be achieved by nanoscale material- or cell-penetrating peptide (CPP)-mediated direct delivery of Nanog-C/CD2 peptides into somatic cancer cells." (PMID 35220392, 2022). "Additionally, IC50 of the mentioned anti-cancer drugs, especially Nelarabine, is highly positively correlated with the expressions of CD2, ZNF683 and KLRB1, which means drug resistance." (PMID 36090993, 2022). "On the other hand, the capability of Nanog-C and CD2 in promoting open chromatin formation might act as an additional positive effect to enhance genotoxic therapy-induced cancer cell death since open chromatins display higher sensitivity to DNA damages than condensed counterparts." (PMID 35220392, 2022). "Future research should prioritize the development of therapeutic strategies, such as CD2 agonists, to restore CD58 expression in hematological tumors or to circumvent the CD2-CD58 axis to target CD58- immuno-resistant cancer cells." (PMID 40365344, 2025). "Exosomes expressing those epitopes are known for being excreted into the bloodstream by T-cells (CD2 and CD3), NK-cells (CD56) and cancer cells (CD146)." (PMID 38902710, 2024). "This review explores our current understanding of the functions of CD2 and CD226, placing a special emphasis on their potential as novel agonist targets for cancer immunotherapy." (PMID 39349829, 2024). "For example, CD3E and CD2 were highly expressed in T cells, CD79A was highly expressed in B cells and KRT18 was highly expressed in cancer cells." (PMID 36681772, 2023). "CD2, CD48, and CD58, closely related to the immunoglobulin superfamily, are involved in T cell responses to cancer cells." (PMID 37904707, 2023). "Moreover, the PT complex upregulated the expression of specific potential cancer suppressor genes, such as cyclin G2, V-set and transmembrane domain containing 4 (VSTM4), coiled-coil domain containing 149 (CCDC149), CD2 molecule, and cyclin G2." (PMID 38027033, 2023).
cancer (continued). "In specific, TIS is referred to as an 18‐gene signature (CCL5, GZMK, CD3D, CD3E, CD2, HLA‐DRA, IL2RG, NKG7, CIITA, CXCR6, LAG3, TAGAP, HLA‐E, CXCL13, IDO1, CXCL10, STAT1, and GZMB), which was related to the response to ICIs in various cancers." (PMID 37434432, 2023). "Finally, we extracted the top 20 in-degree and top 20 out-degree genes as the hub nodes of each cancer and identified six co-owned immune feature genes (CD48, GPR65, C3AR1, CD2, CD3E and ARHGAP9) in these cancers." (PMID 35069897, 2022). "In the process of module analysis and characteristic molecular screening, we selected two characteristic modules and 10 characteristic molecules (PTPRC, CD2, CD69, IRF8, CCR7, CCL5, il2rb, CXCL10, CCR5, TBX21), which could be used as biomarkers of cancer stem-like cells for GIST patients." (PMID 34925310, 2021). "Therefore, it is hypothesized that this CD2-normalized CD14 signal could serve as a valuable metric in predicting features for the presence of aggressive, clinically significant cancer." (PMID 34685549, 2021). "The CD4+ T cells obtained from two different healthy donors were polyclonally stimulated with anti-CD3/CD28/CD2 moAb-coated beads and with IL-2 for 12 days, then subsequently polyclonally restimulated for next 3 days without IL-2 in the presence or without MDA-MB-231 cancer cells." (PMID 34439305, 2021).
infection (41 papers, 2010 to 2025). The state of being infected such as from the introduction of a foreign agent such as serum, vaccine, antigenic substance or organism. "The expression pattern of CD2 gene in pathogenic infection has proven that CD2 is a factor involved in immunity." (PMID 30997371, 2019). "When different subpopulations of IgM+ B cells were analyzed, all three infections caused a substantial decrease in the proportion of naive CD2+CD21+ B cells compared to GF controls." (PMID 25186625, 2014). "However, CD28-deficient and CD2/CD28 deficient mice are able to clear infection, although such clearance is delayed." (PMID 33669726, 2021). "However unfortunately, CD2 levels rapidly and dramatically changed as soon as PBMC or CD4+ T cells were cultured ex vivo, precluding the analyses of a potential association between CD2 expression and infection in cell culture experiments." (PMID 28953327, 2017). "γδ-TCR+ cells are considered rapid responders to infection with multiple protective roles and can be separated into naïve- (CD2−CD8α−, cluster 5), activated- (CD2+CD8α−, cluster 4), and effector- (CD2+CD8α+, cluster 8) γδ-TCR+ cells." (PMID 41510007, 2025). "Overall, these supervised machine learning models are in concordance with our differential expression testing and highlight the prominent roles of CCR5, SLAM and CD2 as markers of HIV-1 in vitro infection." (PMID 36536105, 2023). "Infection associated receptor encoding genes include CCR1 (encoding a receptor for CCL5), CRLF2 (cytokine receptor like factor 2), IL10RA, TLR2, CD2, CD48 and IL7R." (PMID 35061738, 2022). "To further identify possible virological processes that are affected by CD2 prestimulation, we performed stepwise mapping of the viral early infection steps." (PMID 34765923, 2021). "Overall these data demonstrate that γδ T cells produce cytokines ex vivo early post infection, but that H1N1pdm09 in vitro stimulation increases cytokine production in CD2+ γδ T cells from 7 to 13 DPI." (PMID 33603740, 2020). "In the case of infection with Streptococcus iniae, CD2 increased in the head kidney and spleen, respectively, 1 hour after the infection." (PMID 30997371, 2019). "We also report the expression level of CD2 gene when anthropogenic infection with bacterial or viral pathogens was induced." (PMID 30997371, 2019). "In the head kidney, CD2 increased 1 hour after infection with Edwardsiella tarda, maintained the same value until day 1, and decreased to the normal level 3 days later." (PMID 30997371, 2019). "A total of 8,477 gene probes were regulated by all interventions, with 1,331 gene probes modulated by Dex, while 6,696 were modulated by CD2-a infection." (PMID 29867993, 2018). "It is also possible, and probably more likely, that two molecules were needed in stimulation by EC+: CD2 and another factor; thus, blocking CD2 would reduce the infection rates." (PMID 30285810, 2018). "Of note, patients’ PBMC expressing low levels of CD2 were infected more efficiently (mean infection rate 1.43% p24+ cells) than those expressing high amounts of CD2 (mean infection rate 0.59%)." (PMID 28953327, 2017). "The absolute numbers of this γδ T cell subset in blood showed no infection-related changes, whereas the percentages of CD8α+CD27+ γδ T cells within CD2+ γδ T cells in lymph nodes was slightly enhanced in infection groups." (PMID 28559930, 2017). "CD2-Egr2/3−/− mice had more severe infection and inflammatory pathology in the lungs than did WT mice." (PMID 28455436, 2017). "Although CD2-Egr2/3−/− and CD2-Egr2 mice had opposite patterns of clonal expansion and differentiation, both lines had more severe infection than WT mice with impaired viral clearance." (PMID 28487311, 2017). "While the percentage of the CD2−CD8α− phenotype increased significantly in INOC gilts after infection, the percentages of both CD2−CD8α+ and CD2+CD8α+ γδ T cells were significantly decreased in INOC gilts." (PMID 25497114, 2014).